TRIM29 (tripartite motif containing 29)
Diseases named in the same sentence as TRIM29 in open-access papers (continued):
Sharing a sentence is not in itself a finding about the gene and the disease.
esophageal cancer (1 paper, 2023). A primary or metastatic malignant neoplasm involving the esophagus. "TRIM29 was downregulated in ESCA relative to normal specimens, and the TRIM29 deficiency was associated with malignant clinicopathological characteristics in esophageal cancer, including advanced T/N/M stage, histologic grade, metastasis, and poor survival." (PMID 37365152, 2023). "In addition, TRIM29 deficiency correlated with aggressive phenotype and poor prognosis in esophageal cancer." (PMID 37365152, 2023). "Notably, this TRIM29 deficiency was caused by the hypermethylation of its promoter in esophageal cancer." (PMID 37365152, 2023). "This study examined the expression, clinical significance, and biological functions of TRIM29 in esophageal cancer." (PMID 37365152, 2023). "We found that TRIM29 expression was frequently down-regulated, induced by promoter hypermethylation in esophageal cancer and precancerous lesions." (PMID 37365152, 2023). "Consistent with this, correlation analysis in esophageal cancer samples showed that TRIM29 expression was negatively correlated with IL6 expression in TCGA ESCC and GSE21293 datasets." (PMID 37365152, 2023). "It showed that the methylation levels of TRIM29 promoter in esophageal cancer, including ESCC and EAC, were significantly higher than in normal tissues." (PMID 37365152, 2023). "Through GSEA analysis, we found that in esophageal cancer tissues with low TRIM29 expression, many genes of these two HALLMARKs were highly expressed, suggesting that these tissues proliferated more vigorously." (PMID 37365152, 2023). "Functionally, TRIM29 overexpression markedly hinders proliferation, migration, invasion, and epithelial–mesenchymal transition of esophageal cancer cells, whereas opposing results are observed when TRIM29 is silenced in vitro." (PMID 37365152, 2023). "Taken together, these results demonstrate that TRIM29 is downregulated in ESCA and its precursor lesions, highlighting that TRIM29 deficiency is a marker of early-stage esophageal cancer and may contribute to the tumorigenesis of ESCA." (PMID 37365152, 2023). "Among the 20 assigned cancer types compared with normal tissues, under the criteria of a fold‐change of 1.5 and p-value of 0.05, TRIM29 mRNA levels were downregulated in 22 datasets with eight different types of cancer, including three datasets of esophageal cancer." (PMID 37365152, 2023). "TRIM29 has been reported to inhibit cytokine production, such as IL6, and TRIM29 knockdown markedly enhanced the production of these cytokines, which could activate STAT3 in multiple tumors, including esophageal cancer." (PMID 37365152, 2023). "TRIM29 hindered the proliferation, migration, invasion, metastasis, and EMT of esophageal cancer." (PMID 37365152, 2023). "Therefore, we hypothesized that TRIM29 might positively regulate the expression of ZNF750 and mediate its inhibitory function in invasion and metastasis of esophageal cancer." (PMID 37365152, 2023).
esophageal squamous cell carcinoma (1 paper, 2024). Esophageal squamous cell carcinoma (ESCC) is a type of esophageal carcinoma (EC) that can affect any part of the esophagus, but is usually located in the upper or middle third. "For instance, our recent research demonstrated that hypermethylation of the TRIM29 promoter led to its downregulation, thereby promoting tumor metastasis in esophageal squamous cell carcinoma." (PMID 38504159, 2024).
gastric ulcer (1 paper, 2024). An ulcerated lesion in the mucosal surface of the stomach. "In subsequent studies, it is necessary to use TRIM29 gene knockout mice to confirm the key role of TRIM29 in the treatment of gastric ulcers." (PMID 38213743, 2024). "Erk/Akt/TRIM29 axis may be one of the potential targets for MSC to play a therapeutic role in gastric ulcer healing." (PMID 38213743, 2024). "Due to the lack of TRIM29-specific inhibitors, we did not validate the role of TRIM29 in gastric ulcers in animals in this study." (PMID 38213743, 2024). "No reports exist on whether TRIM29 plays a role in the healing of gastric ulcers." (PMID 38213743, 2024).
glioma (1 paper, 2025). A benign or malignant brain and spinal cord tumor that arises from glial cells (astrocytes, oligodendrocytes, ependymal cells). "In the context of glioma initiation and progression, TRIM29 serves as a significant immunosuppressive factor." (PMID 40469294, 2025).
intestinal infection (1 paper, 2025). "Importantly, compared with Ifnar1−/−–Trim29fl/fl mice, Ifnar1−/−Trim29IEC-KO mice survived much better from EMCV intestinal infection, suggesting that the antiviral phenotype of TRIM29 knockout mice results from TRIM29-mediated regulation of type III IFN and inflammasome activation." (PMID 39396665, 2025).
kidney injury (1 paper, 2024). Trauma to the kidney. "Thus, further validation of the upstream and downstream relationship between TRIM29/TRIM18 and STING in various renal diseases is necessary to determine whether TRIM29/TRIM18 can effectively regulate STING, thereby controlling acute and chronic kidney injury, as well as renal cancer." (PMID 39114669, 2024).
oral squamous cell carcinoma (1 paper, 2022). "And miRNA-34c-5p has been shown to exert oncogenic effects in renal cell carcinoma, oral squamous cell carcinoma and other tumors by targeting MMP2 and TRIM29 to inhibit cell proliferation, invasive and migration." (PMID 36203485, 2022).
renal carcinoma (1 paper, 2024). A carcinoma arising from the epithelium of the renal parenchyma or the renal pelvis. "However, it is imperative to further investigate the extent and proportion of pyroptotic cell death mediated by TRIM29 in both normal kidney and renal cancer cells." (PMID 39114669, 2024).
respiratory infections (1 paper, 2021). "Several tripartite motif proteins (TRIMs) are also upregulated in the network, and TRIM29 is reported to be involved in macrophage activation in response to respiratory infections." (PMID 34439814, 2021).
Respiratory tract infection (1 paper, 2024). An infection of the upper or lower respiratory tract. "Considering this dual role in both innate immune modulation and stress response, epithelial-derived TRIM29 potentially impacts PA respiratory tract infection." (PMID 39691712, 2024).
Rotavirus infection (1 paper, 2025). Infection with any of the rotaviruses. "The Trim29−/− suckling mice exhibited over 3-fold increase in IFN-λ3 and IL-18 production compared to their wild-type Trim29+/+ counterparts following rotavirus infection." (PMID 39396665, 2025). "Next, we investigated the kinetics of IFN-λ3 and IL-18 production in primary IECs from mouse intestine organoids of both Trim29+/+ and Trim29−/− mice at 10 h, 20 h, and 30 h after Rotavirus infection." (PMID 39396665, 2025). "We found that knockout of TRIM29 led to the peak production of IFN-λ3 and IL-18 at 20 h post-infection, with a subsequent decrease at 30 h after Rotavirus infection." (PMID 39396665, 2025). "Additionally, although NLRP6 and NLRP9b were barely expressed in human HT-29 IECs, NLRP6 and NLRP9b were induced in HT-29 IECs after EMCV and rotavirus infection, respectively, suggesting thatNLRP6 and NLRP9b control the upregulation of IFN-λ3 and IL-18 upon knock down of TRIM29." (PMID 39396665, 2025).
skin cancer (1 paper, 2010). "It would be interesting to compare the abundance of TRIM29 in transformed keratinocytes and in skin cancer." (PMID 20454669, 2010). "In this view, TRIM29 could be a protein involved in skin cancer." (PMID 20454669, 2010).
skin squamous cell carcinoma (1 paper, 2020). A carcinoma arising from the squamous cells of the epidermis. "Loss of TRIM29 expression promotes invasion of skin squamous cell carcinoma cells by altering distribution of keratins." (PMID 33055416, 2020).
systemic lupus erythematosus (1 paper, 2022). An autoimmune multi-organ disease typically associated with vasculopathy and autoantibody production. "For example, PSMB9 in systemic lupus erythematosus (SLE) and TRIM29 in SCC were obtained through proteomic screening, and further functional studies were conducted precisely." (PMID 36338621, 2022).
ulcer (1 paper, 2024). "We used WB and immunohistochemistry to confirm that the expression of Trim29 around the ulcer area was decreased in the Model group, but significantly increased in the MSC and MSC-CM groups." (PMID 38213743, 2024).
ulcerative colitis (1 paper, 2026). An inflammatory bowel disease involving the mucosal surface of the large intestine and rectum. "Subsequent validation confirmed that TRIM29 was upregulated in Ulcerative colitis (UC) across human datasets: its mRNA expression was lowest in healthy colon tissue and highest in active UC in both GSE75214 and GSE107597." (PMID 41601651, 2026). "To investigate the immunological role of TRIM29 in ulcerative colitis (UC), we first analyzed bulk transcriptomic data." (PMID 41601651, 2026).
urothelial carcinoma (1 paper, 2022). A malignant neoplasm derived from the transitional epithelium of the urinary tract (urinary bladder, ureter, urethra, or renal pelvis). "Both PHGDH and TRIM29 exhibited significant expression in SCC of the lung and urothelial carcinoma." (PMID 35204409, 2022).
cancer (58 papers, 2014 to 2026). A tumor composed of atypical neoplastic, often pleomorphic cells that invade other tissues. "Specifically, TRIM14, TRIM25, TRIM32, TRIM44, TRIM59, and TRIM29 exhibit abnormal expression in different cancer types and have been linked to patient prognosis." (PMID 39273003, 2024). "In this study, we seek to carry out a meta-analysis to evaluate the overall risk of TRIM29 for survival in patients with cancers." (PMID 29552313, 2018). "Increasing evidence showed that aberrant expression of TRIM29 was associated with clinical outcomes for cancer patients." (PMID 29552313, 2018). "TRIM29 has been known to associate with β-catenin pathway in few other cancers." (PMID 40420099, 2025). "Next, we investigated the role of TRIM29 in cancer via Cancer Hallmark Analysis Tool." (PMID 40420099, 2025). "Similar findings were observed in our study, STAT3 inhibition could effectively reverse the cancer-promoting function of TRIM29 deficiency in ESCC." (PMID 37365152, 2023). "Current research on TRIM29 is predominantly in oncology, where it exhibits distinct and sometimes opposing effects across cancer types." (PMID 41601651, 2026). "This bacterial mimicry parallels the TRIM29-dependent immune dampening pathways observed in chronic infection and cancer, underscoring a shared evolutionary blueprint for immune evasion." (PMID 40607404, 2025). "TRIM29 essentially participate in several biological functions pertaining to cancer growth and metastatic progression in several cancer types." (PMID 40420099, 2025). "Although TRIM29 is primarily an E3 ubiquitin ligase, our in silico findings indicate that TRIM29 contributes to multiple hallmarks of cancer pertaining to tumor progression and chemo-resistance." (PMID 40420099, 2025). "We observed that TRIM29 contributed to 5 hallmarks of cancer i.e., invasion and metastasis, inducing angiogenesis, sustaining proliferative signaling, resisting cell death, and contributing to genome instability." (PMID 40420099, 2025). "Ataxia-telangiectasia group D-complementing (ATDC), also known as tripartite motif 29 (TRIM29), is a member of the TRIM protein family, highly expressed in various cancers and associated with prognosis and survival rates." (PMID 39839479, 2024). "TRIM29 is an E3 ubiquitin ligase, and TRIM29-mediated protein ubiquitination has been shown to play pivotal roles in antiviral innate immunity and cancer development." (PMID 38664417, 2024). "Conversely, TRIM29 downregulation was detected in prostate cancer, cutaneous head and neck squamous cell carcinoma and breast cancer, in which cancer cell migration and invasion were elevated." (PMID 39451518, 2024). "TRIM29 promoted cancer progression by exhibiting the CSC-like features of cancer cells in an m6A-YTHDF1-dependent way." (PMID 36707507, 2023). "TRIM29 mediates diverse physiological and pathological processes, including cell differentiation, immunity, and cancer." (PMID 37365152, 2023). "Galectin-9 augmented an immunosuppression in TME via accelerating TRIM29-mediated degradation of STING in human cancers." (PMID 36733484, 2023). "TRIM29 is abnormally expressed in many malignant tumours and is involved in the proliferation and metastasis of cancer cells." (PMID 37671092, 2023). "It has been found that TRIM29 was highly expressed in human cancers and correlated to cancer occurrence." (PMID 36707507, 2023). "It seems necessary to re-evaluate TRIM29 expression patterns and its probable molecular functions based on cancer type and patient’s ethnic background." (PMID 35845310, 2022). "While TRIM29 acts as an oncogenic factor in most tumors, it plays a tumor suppressor role in other cancers." (PMID 35845310, 2022). "Meanwhile, TRIM29 is also engaged in the occurrence and development of different diseases, including cancer, inflammatory diseases, infectious diseases, neuropsychiatric diseases, chromosome abnormalities, and developmental diseases." (PMID 36249749, 2022).
cancer (continued). "Previous cell experiment studies revealed the important roles of C- and N-terminal portions of TRIM29 proteins in cancers." (PMID 35054873, 2022). "The function of miR-122 and its associated mRNAs such as TRIM29, Bcl-W, CCNG1, CDC25A, XIAP, and ALDOA are reportedly downregulated during cancer cell progression." (PMID 36499586, 2022). "The study eventually included 2,046 eligible patients, and the results suggested an important relationship between TRIM29's expression upregulation and a poor prognosis in patients with malignant tumors." (PMID 36568638, 2022). "This dichotomic phenomenon is simultaneously observed for specific TRIM proteins (e.g., TRIM29) in different cancers." (PMID 34988104, 2021). "The expression level of TRIM29 protein is particularly related to advanced malignant tumor stage and cancer drug resistance in NPC." (PMID 34988104, 2021). "Meanwhile, BECN1 knockdown can inhibit the autophagy degradation of E-cadherin promoted by TRIM29 overexpression and cancer cell metastasis." (PMID 32640423, 2020). "Tripartite motif protein 29 (TRIM29) is dysregulated in various cancer and functions as oncogene or tumor suppressor in discrete cancers." (PMID 32994394, 2020). "The role of TRIM29 has been studied extensively in various cancers, but the conclusions are inconsistent." (PMID 29552313, 2018). "Overall, in subgroup analysis, the results confirmed that relationship between high expression of TRIM29 and prognosis in patients was affected by cancer location, ethnicity of the study subjects, detection method, pathologic type and data source." (PMID 29552313, 2018). "Pooled Hazard ratios (HRs) with 95% confidence intervals (CIs) for patient survival and disease recurrence were calculated to investigate the correlation between TRIM29 expression and cancer prognosis." (PMID 29552313, 2018). "Recent studies have shown that tripartite motif-containing protein 29 (TRIM29) had prognostic values in several cancers." (PMID 29552313, 2018). "For example, TRIM29 has been reported to be upregulated in multiple tumor tissues and its overexpression can promote cancer development and progression." (PMID 26799420, 2016). "Correlation analysis showed that TRIM29 protein overexpression was significantly associated with advanced FIGO Stage (p=0.026), pelvic lymph node metastasis (PLNM, p=0.002) and cancer relapse (p<0.001)." (PMID 27081037, 2016). "Although some studies on TRIM29 in cancer have been reported, little is known about the biological function and mechanism of TRIM29 in cancer." (PMID 27081037, 2016). "We selected TRIM29 because of previous findings that revealed opposing functions of this gene in various cancers." (PMID 24651077, 2014). "To elaborate on the alterations in TRIM29 regulation between various normal tissues and the corresponding carcinomas, we analyzed promoter methylation and gene expression in TCGA data base." (PMID 24651077, 2014). "Literature reports suggest that the function of TRIM29 in cancer may be cell line dependent, in that it has been shown to act as both a tumor suppressor or an oncogene." (PMID 40362175, 2025). "The binding of the YTHDF1 protein to m6A-modified TRIM29 promotes the translation of TRIM29 in cisplatin-resistant OC cells, enhances the cancer stem cell characteristics in cisplatin-resistant OC cells, and then promotes the development of malignant tumours." (PMID 40356909, 2025).